TNF (tumor necrosis factor)
Diseases named in the same sentence as TNF in open-access papers (continued):
Sharing a sentence is not in itself a finding about the gene and the disease.
cancer (continued). "Collectively, TNF-α seemed not to be a cytokine suppressing Pax7 and myogenic differentiation in cancer cachexia." (PMID 30300394, 2018). "Major CTL activities are mediated either directly, through synaptic exocytosis of cytotoxic granules containing perforin and granzymes into the target, resulting in cancer cell destruction, or indirectly, through secretion of cytokines, including interferon (IFN)γ and tumor necrosis factor (TNF)." (PMID 29403496, 2018). "Although, there was no study about the association of IL-1β C-511 T and TNF-α G308A polymorphisms on ICC risk until now, the study on cytokines expression related cancer has been reported which acts as a diagnostic marker for cancer." (PMID 30139338, 2018). "In contrast to TNF, pre-clinical investigations have shown that TRAIL can selectively induce apoptosis in cancer cells without causing damage to normal cells." (PMID 29983892, 2018). "Tumor necrosis factor (TNF)-related apoptosis-inducing ligand (TRAIL) is a member of the TNF superfamily that selectively triggers apoptosis in cancer cells, but not in normal cells." (PMID 29531826, 2018). "Our novel findings also showed that BAY 11‐7082 suppressed the acidic bile‐induced miR‐192 levels in treated human hypopharyngeal cells with strong positive correlations between BAY 11‐7082‐induced miR‐192 levels and inflammatory and key cancer molecules, such as RELA(p65), STAT3 and TNF‐α." (PMID 29516639, 2018). "For instance, cachectic cytokines such as tumour necrosis factor-α (TNF-α), interferon-γ (IFN-γ), and different interleukins (ILs., e.g. IL-1β and IL-6) may be increased in the peripheral circulation of cancer patients and induce cancer cachexia." (PMID 29609556, 2018). "In contrast to young individuals, aged individuals have consistently elevated levels of inflammatory cytokines, especially interleukin-6 (IL-6) and tumor necrosis factor-α (TNF-α), which may induce muscle atrophy and cancer through DNA damage." (PMID 29564335, 2018). "Although cytotoxic in various cancer cells, tumor necrosis factor (TNF)-related apoptosis-inducing ligand (TRAIL) does not trigger apoptosis in most non-transformed cells." (PMID 29717117, 2018). "CC patients showed higher value of IL-8 (55.6-fold) but not IL-6 (9.8-fold) and TNF-α (1.6-fold) when compared with the control and with weight-stable cancer group." (PMID 30513776, 2018). "In this study, higher serum levels of IL-1β, IL-6, IL-8, and TNF-α were observed in cancer patients of the locally advanced group than those of the normal and resected groups." (PMID 30513776, 2018). "ADAM substrates include many cancer-related proteins, such as Notch receptors and their ligands, epidermal growth factor receptor (EGFR) ligands, interleukin-6 receptor (IL-6R), tumor necrosis factor (TNF) and its receptors, E-cadherin, and CD44." (PMID 28148288, 2017). "Tumor necrosis factor (TNF)-related apoptosis-inducing ligand (TRAIL) selectively triggers apoptosis in various cancer cells but not in normal cells." (PMID 29290980, 2017). "The IR per 10,000 PY of malignancies was lower in TNF inhibitor users (81/10,000 PY) compared with bDMARD nonusers (117/10,000 PY) in the BSRBR, and was 53.5/10,000 PY in bDMARD users and 74.1/10,000 PY in bDMARD nonusers from the Taiwan national database." (PMID 29246243, 2017). "TNF-α is normally not detectable in plasma or serum of healthy individuals but can be detected in some cancer patients, almost invariably those with advanced disease and poor prognosis." (PMID 28107185, 2017). "The proinflammatory cytokine, TNF-α, is an inducer of EMT inseveral cancers." (PMID 28388726, 2017). "Based on previous studies, where IFN-γ was shown to enhance TNF-α receptor expression in cancer cells, we wanted to test whether IFN-γ may sensitize LLC cancer cells to TNF-α treatment." (PMID 29276511, 2017).
cancer (continued). "Natural killer (NK) cells are lymphocytes of the innate immune system that exhibit cytotoxicity toward cancer cells and virus-infected cells and have the capacity to produce cytokines such as interferon-γ (IFN-γ) and tumor necrosis factor-α (TNF-α) in response to stimuli." (PMID 28386260, 2017). "CAFs promote cancer cell growth and metastasis by secreting various growth factors and cytokines, including TGFβ, stromal cell-derived factor-1 (SDF-1), CXCL1, tumor necrosis factor-α (TNFα), as well as microRNAs and exosome." (PMID 29100297, 2017). "These include TNF-α antagonists which are used for the treatment of chronic inflammatory diseases and EGCG which is in various clinical trials for the treatment of cancer." (PMID 29163050, 2017). "We showed that pro-inflammatory and anti-inflammatory cytokines IFNγ, TNFα, and IL-10 did not induce expression of B7x on human or murine cancer cells." (PMID 29137299, 2017). "For example, several pro-inflammatory cytokines, including interferon gamma (IFN-γ), tumor necrosis factor alpha (TNF-α), transforming growth factor beta (TGF-β), and interleukin-10 (IL-10), have been shown to contribute to both the initiation and development of cancer." (PMID 29268703, 2017). "In order to overcome these unwanted secondary effects of TNF-α, the targeted delivery strategy using CYT-6091 has been tested in a phase I clinical trial in advanced stage cancer patients including breast ductal carcinoma and plans for a phase II trial are ongoing." (PMID 29202842, 2017). "TNF-α can also induce the expression of many oncoproteins through NF-κB or p38 signaling, such as JAG1, Fascin, VEGF and MMP2/MMP9, to promote the development of cancers." (PMID 28938560, 2017). "Bone marrow adipocytes also secrete several pro-inflammatory mediators such as IL-1B, IL-6, leptin, adiponectin, vascular cell adhesion molecule 1 (VCAM-1), tumor necrosis factor alpha (TNF-alpha) and CXCL12 that increase bone tropism, proliferation, and survival of certain cancer cells." (PMID 28800754, 2017). "Thus, we conclude that TNF-α/TNFR1 activates the NF-κB (and/or p38)/STAT3/HBXIP signaling, leading to the development of cancer." (PMID 28938560, 2017). "It is known that TNF-α can activate SPHK1 in endothelial cells promoting anti-apoptotic effect; thus, TNF-α may be a trigger of the S1P pathway, mainly by activating SPHK1, favoring the cancer development." (PMID 29186783, 2017). "TNF-α may be the major contributor of SOD-2 upregulation as well as EMT and migration in cancer cells." (PMID 28801561, 2017). "In addition, we stimulated (for 30 min) BJ cells with tumor necrosis factor α (TNF-α), a cytokine that is known to play an important role in cancer progression and inflammation." (PMID 29263424, 2017). "We found AFG1 did not promote SOD-2 expression and EMT in cancer cells, but enhanced TNF-α and SOD-2 expression in MΦ-THP-1 cells." (PMID 28801561, 2017). "Surprisingly, we found that TNFα-mediated cancer cell killing through its canonical receptor TNFR1 is not required for anticancer immunity and therapeutic response in vivo." (PMID 28839138, 2017). "In addition, the combination therapy enhanced systemic anti-cancer immunity by increasing the abundances of T cell populations expressing IFN-γ and TNF-α." (PMID 28212561, 2017). "Since stimulating MCF7 cells with TNF-α increases CD47 expression, we then blocked the TNF pathway as a possible translational approach to reduce CD47 expression and aid phagocytosis of the cancer cells." (PMID 28378740, 2017). "Conditioned media derived from Nur77-/- peritoneal macrophage (CM2) significantly promotes cancer cells migration and invasion compared with conditioned media derived from Nur77+/+ peritoneal macrophage (CM1), which is greatly reversed by TNF-α blocking antibody." (PMID 28170411, 2017).
cancer (continued). "Two well-known cytokines that may be potentially useful for cancer immunotherapy are IFN-γ and tumor necrosis factor-α (TNF-α)." (PMID 29276511, 2017). "Further studies are required to elucidate the true negative rate and the statistical power of this study to show significant differences in plasma IL-6, TNF-α and monocyte HLA-DR expression between patients with and without cancer." (PMID 28692671, 2017). "Although growing evidences emphasized on the importance of miR-105 in cancers, none of previous studies systematically investigated its role in TNF-α-induced metastasis in human CRC." (PMID 29238068, 2017). "Moreover, H. pylori has been shown to induce the secretion of several pro-inflammatory mediators such as TNF-α, IFN-γ, IL-1β, IL-6, and IL-8 by infected cells showing its contribution in inflammation-induced cancer." (PMID 28632155, 2017). "TNF-α (25 pg/mL) stimulated extracellular expression of CD62E while adhesion assays, under both static and physiological flow live-cell conditions, explored the effect of CD15s-mAb immunoblocking on adhesion of cancer cell–brain endothelium." (PMID 28698503, 2017). "On one hand, lack of Nur77 in macrophages promoted inflammatory cytokine TNF-α production, which stimulated cancer cells to undergo EMT and endowed them invasive properties." (PMID 28170411, 2017). "Mechanistically, hypertonicity-induced TNF production can substitute in SM-sensitized cancer cells for lack of SM-triggered TNF release." (PMID 28771230, 2017). "Cancer cells, especially those with cancer stem-like cells (CSCs) activity, such as triple negative breast cancer cells (TNBCs), secret effector cytokines, including IFN-γ, TNF-α, and IL-1β that activate MSCs immunosuppressive role." (PMID 27493669, 2016). "Tumor related apoptosis-inducing ligand (TRAIL) is a transmembrane protein of the TNF (tumor necrosis factor) gene superfamily that triggers apoptosis in cancer cells, but not in normal cells." (PMID 26955956, 2016). "Mounting evidence suggests that SAB is capable of preventing the development of cancer, and that anti-inflammatory mechanisms of SAB could involve modulation of cytokines, the COX-2/PGE-2 pathway, NF-κB, TNF-α, and MMPs23." (PMID 27278104, 2016). "In addition to downstream targets of NFκB, we also recovered important upstream regulators for cancer development and progression, including STAT3, MAP3K8, and TNF." (PMID 27078000, 2016). "Cells from each of the tumors were incubated with no drugs, SM-164, TNFα or both, coupled with a range of doxorubicin concentrations up to that detected in the blood of treated cancer patients." (PMID 27129149, 2016). "Cancer cells may induce up-regulation of different adipocyte-secreted factors as TGF-beta, TNF-alpha and MMP." (PMID 26958939, 2016). "The presence of a specific TGFβR inhibitor was able to inhibit the conversion to IL-10 production by irradiated cancer cells; however, the TGFβR inhibitor was not able to restore TNFα production by macrophages." (PMID 27602953, 2016). "Moreover, ISG15 abolishes TNF-α-activated NF-κB signaling and decreases the transcription of NF-κB-modulated genes including XIAP and Mcl-1, two oncogenes in various cancers." (PMID 27659523, 2016). "Regulating cell growth through TNF-alpha and CAV1 is another way that flavonoids might affect cancer." (PMID 27023590, 2016). "Since TNF-α, through NF-κB, is known to regulate the expression and activity of β-catenin, Snail and GSK-3β40, our results indicate that NF-κB plays an indispensable role in implementing the anti-cancer program triggered by AECHL-1." (PMID 27974826, 2016).
cancer (continued). "Rather than protecting against cancer, growing evidence indicates that TNF-α can promote the development of cancer." (PMID 28115787, 2016). "Alleviation of cancer-related symptoms by MR16-1 treatment seems to contribute to the reduction of TNF-α and IL-1β levels rather than the MR16-1 treatment having a direct impact on their levels by the blockade of IL-6 signaling." (PMID 27068103, 2016). "Cancer cell can expresses and release soluble ICAM1, that is regulated by TNF-α and INF-γ." (PMID 28105922, 2016). "This suggest the anti-cancer potential of this compound possibly without the adverse effects seen in TNF-α, which warrants further investigation of this compound." (PMID 27070314, 2016). "TNF-α is considered to be one of the strongest physiological inducers of MMP9 expression, the enzyme which appears necessary for sustained migration of various cell types, including cancer cells." (PMID 27042827, 2016). "In the context of cancer immunotherapy, the innate antiviral inflammatory response to PVSRIPO could enable the production of such antitumor immunity directly (TNF-α and NK-cell mediated killing) and indirectly (antitumor T cell and antibody responses)." (PMID 27806313, 2016). "We selected four mRNAs that are well studied in cancer: PIM1, HIF1A, TNFα, and c-MYC34." (PMID 26926077, 2016). "The novelty found in this work was that BF-rTK + GCV triggered TNF-β (not TNF-α) to induce cancer cell apoptosis in vitro TNFR2 (not TNFR1)." (PMID 27464624, 2016). "Tumor necrosis-factor (TNF)-related apoptosis-inducing ligand (TRAIL) is a member of the TNF-superfamily that selectively induces apoptosis through death receptors (DRs) 4 and/or 5 in cancer cells." (PMID 26304927, 2015). "In stem cells and cancer cells, MMP2 and MMP9 are regulated by cytokines such as TGFβ2 and TNFα." (PMID 25774514, 2015). "In GBM cells, ICAM-1 expression has been shown to increase following stimulation with proinflammatory cytokines, such as interleukin-1β (IL-1β), tumor necrosis factor-alpha (TNFα), and interferon-gamma (IFN-γ), indicating that ICAM-1 is one of the inflammatory mediators also in this type of cancer." (PMID 26798546, 2015). "Moreover, N-6 inhibits tumor necrosis factor α (TNFα)-induced AKT activation and enhances TNFα-mediated cancer cell apoptosis in an RXRα/tRXRα dependent manner." (PMID 26156677, 2015). "Tumor necrosis factor (TNF)-related apoptosis-inducing ligand (TRAIL) induces apoptosis in various types of cancer cells without damaging normal cells." (PMID 26506422, 2015). "In addition, lovastatin induced the expression of TNF-α, and gefitinib enhanced lovastatin-induced antiproliferation through collaborating TNF-α expression in both cancer cell lines." (PMID 26160843, 2015). "Thus, we proceeded with the gene expression analysis of the NF-κBp65 pro-inflammatory target genes by qPCR, having found that IL-1β, TNF-α and MCP-1 expression were upregulated in cachectic cancer patients compared with controls." (PMID 26053616, 2015). "Although the role of TNF-α during the inflammatory process in cachexia induced by cancer has been extensively studied, there is no consensus about the degree of influence of this cytokine on this inflammatory process." (PMID 26508818, 2015). "Negative regulation of TNF levels by miR-21 therefore may not just help dampen down excessive inflammation but may also explain the effects of miR-21 on cell proliferation, migration, invasion, and transformation associated with excessive miR-21 levels and cancer." (PMID 25688245, 2015). "Our studies indicated that TNF α segment containing amino acid residues 75–94 (named as P16, LLTHTISRIAVSYQTKVNLL) could selectively bind to TNFRI and has good anti-cancer activity (unpublished data)." (PMID 26337231, 2015).
cancer (continued). "Similarly, treatment of Caski and CSCC1 cancer cells with entinostat resulted in a higher production of CCL2, IL-8 and CXCL9 by the cancer cells when stimulated with IFN-γ and TNF-α than dimethylsulphoxide carrier control-treated cells." (PMID 26055519, 2015). "Moreover, several inflammatory cytokines such as TNF-α, IL-6, TGF-β, and IL-10 have been shown to participate in both the initiation and progression of cancer." (PMID 26528286, 2015). "Immunohistochemical staining for TNF-α was more intense in malignant neoplasms compared with benign neoplasms, but this difference was not statistically significant (P=0.4495)." (PMID 25624918, 2015). "For example, mice lacking NEMO in hepatocytes develop steatohepatitis and carcinoma, as well as exhibiting severe liver damage when injected with TNF." (PMID 26170532, 2015). "While cytokines such as TNF-α and IL-6 have been known to mediate cancer cachexia, SJDBT reduced IL-6 level without altering TNF-α." (PMID 24963216, 2014). "TRAIL is a member of the tumor necrosis factor super-family that induces a selective apoptosis through the activation of death receptors in cancer target cells, with no relevant effects on healthy cells." (PMID 25089245, 2014). "The few available data on immunological effects of MZ are mostly limited to cancer patients and show that CD8+ T-cell release of IFN-γ and TNF-α may be higher in autologous grafts collected after G-CSF and MZ, compared with G-CSF alone." (PMID 25179788, 2014). "We also determined that the secretion levels of TNF-α and IL-12 were significantly higher in the ascitic fluids of the GPC3-expressing HM-1 cell-infected mice than in the control HM-1 cell-injected mice on day 7 after inoculation with cancer cells." (PMID 24992906, 2014). "Studies on the stimulation of CD40 present on cancer cell lines in the bladder, pancreas, or breast through the recombinant CD40L have shown increased expression of ICAM and Fas by cancer cells and the production of IL-6, IL-8, GROα, GM-CSF, and TNF-α." (PMID 25117071, 2014). "Tumor necrosis factor (TNF)-related apoptosis-inducing ligand (TRAIL), a member of the TNF superfamily, has been considered to be a potential cancer therapeutic agent due to its ability to preferentially induce apoptosis in malignant cells but not in most normal cells." (PMID 24566141, 2014). "Cancer cell lines originating from lung, colon, bladder, liver, breast, skin and cervix were treated with tumor necrosis factor (TNF)-α in presence or absence of BCG infection." (PMID 25208737, 2014). "There were three cases of incident cancer in the “MTX use, biologics-naïve” group, only one in the anti-TNF biologics-containing group and twenty nine in the “both MTX- and biologics-naïve” group, in comparison, there were fifty cases of cancer in the non-JIA comparator group." (PMID 25174953, 2014). "TNFα is one of the initial and important mediators to activate downstream signaling pathways by binding to trimerized TNFα receptors (TNFR), and thus is an ideal drug target for cancer therapy." (PMID 25340707, 2014). "Resveratrol is reported to inhibit cancer cell proliferation and in our assay the presence of resveratrol, in the absence of TNF-α, led to a reduction of DC-induced T cell proliferation." (PMID 24614867, 2014). "Activation the MAP kinase pathway is one of principal components of the TNFα-mediated activation of NFκB signaling, and constitutive MAP kinase activation is also believed to contribute to NFκB-mediated resistance to apoptosis and cell death in cancer cells." (PMID 25329315, 2014).